IL1B (interleukin 1 beta)
Diseases named in the same sentence as IL1B in open-access papers (continued):
Sharing a sentence is not in itself a finding about the gene and the disease.
viral infection (continued). "The importance of the IL-1β/IL-6 pathway as a biomarker of trained immunity has also been highlighted in a model of experimental viral infection following yellow fever vaccination." (PMID 35177621, 2022). "NLRP3 inflammasome mainly controls interleukin-1β (IL-1β) secretion, leading to cell death called pyroptosis constituting a major antiviral host defense and inflammatory diseases upon viral infection." (PMID 35300578, 2022). "The proinflammatory cytokine IL-1β, mainly produced by macrophages, epithelial cells and neutrophils, plays important roles in host defense against virus infection." (PMID 35906635, 2022). "This difference is comparable to that detected after viral infection, and much lower than in neonatal rat cardiomyocytes after Il-1β treatment." (PMID 36362254, 2022). "The secretion of IL-1β and IL-6 has been linked to the recruitment of PMN to the virus infection site, while increased IFN-γ production is indication of T cell response and is involved in the initial monocyte recruitment as well." (PMID 33841400, 2021). "Activation of this gene following viral infection or pro-inflammatory stimulus IL-1β induces switching of the 14th subunit of CIV from NDUFA4-to-MOCCI, accompanied by the biogenesis of miR-147b in the cytosol." (PMID 33837217, 2021). "Viral infections are known to induce production of IL1β through the signaling pathway of inflammasomes." (PMID 34161370, 2021). "Two other crucial cytokines, IL-6 and TNF-α, which generated in abundance by IL-1β stimulation or autocrined from the activated “mononuclear-macrophage system”, are elevated not only in bacterial infection but also during viral infection." (PMID 34059076, 2021). "IL-1β was significantly upregulated in BAL from children with mixed bacterial-viral infections compared with those infected by either bacterial or viral pathogens alone." (PMID 34602860, 2021). "Herein, we showed that BAL Th17 cell-related cytokines, especially IL-1β, were further upregulated in patients with mixed bacterial-viral infections than in those with single-type infections." (PMID 34602860, 2021). "We determine the level of inflammatory marker interleukin (IL)-1β, a transcription activator in the innate immune response to viral infection induced upon infection of A549 cells with HAdV3." (PMID 34926703, 2021). "IFN-γ and IL-1β are crucial for the initiation of protective immunity in many viral diseases but also responsible for immune-mediated tissue damage." (PMID 34209576, 2021). "On the contrary, rhLAV-BPIFB4 induced a rapid increase in IL-18 and IL-1b levels, shown largely protective during the early stages of the virus infection." (PMID 34396395, 2021). "The inflammatory role of IL-6 and IL-1β in viral infections such as respiratory syncytial virus (RSV) and adenovirus has been reported to influence the susceptibility and severity of the respiratory disease." (PMID 33522421, 2021). "After the viral infection, the IL-1β mRNA expression in all groups was enhanced to varying degrees; the group infected with GTPV alone had the highest up-regulation, and the group infected with PPRV alone the lowest expression." (PMID 33827620, 2021). "It is noteworthy that these cytokines, which include tumor necrosis factor alpha (TNF-α) and interleukin 1β (IL-1β), play a critical role in triggering acute-phase responses to viral infection." (PMID 33802995, 2021). "Increasing characteristic proinflammatory cytokine IL-1β levels is an important method of defending against invading viral infection." (PMID 35062226, 2021). "Interleukin-1β (IL-1β) is an inflammatory cytokine that plays an essential role in inflammatory responses against viral infection." (PMID 35062226, 2021). "Proinflammatory cytokines, such as TNF-α and IL-1β, readily detected in the trachea and lung in BoHV-1-infected cattle, contributes greatly to virus infection-induced rhinotracheitis and pneumonia." (PMID 34008469, 2021).
viral infection (continued). "The pro-inflammatory cytokines IFN-γ and IL-1β generally appear in the acute phase of virus infection." (PMID 34209576, 2021). "One subject, who was found to have had a concurrent systemic viral infection, had an increase in IL-1β, IL-6, IL-10, and TNF-α following chDAB4 incubation which appeared to be inversely proportion to chDAB4 concentration used." (PMID 34231102, 2021). "In contrast, an intense increase in IL-1β induced by virus infection or uterus culture with 100 ng/mL recombinant chicken IL-1β resulted in a disturbance of CaBP-D28K expression." (PMID 33167850, 2020). "IL-1β is a central promoter of low-grade inflammation and protection against certain viral infections, including influenza." (PMID 32053590, 2020). "Higher IL-1β levels are also highly relevant to the direct protective effect against viral infection, such as the herpes simplex virus." (PMID 32570833, 2020). "One of the fundamental innate immune responses to viral infections includes the processing and release of pro-inflammatory cytokines such as interleukin (IL-1β and IL-18) through the activation of inflammasome." (PMID 32210961, 2020). "Viral infections trigger the production of pro-inflammatory cytokines, particularly IL-1β and TNF-α, in human pancreatic cells through a TLR4-dependent pathway." (PMID 33071971, 2020). "IL-8 and IL-1β are two major pro-inflammatory cytokines which play a central role in initiation of inflammatory responses against bacterial-and viral-infections." (PMID 32711533, 2020). "ORF2 gene deletion resulted in expression of higher levels of IL-1β cytokine, which is considered as a host defense against virus infection." (PMID 32911663, 2020). "Until now, IL-1β polymorphisms were linked to some other diseases, including pediatric Helicobacter pylori infection, septic shock and seasonal influenza A/H3N2 virus infection." (PMID 32421725, 2020). "Yet, monocytes/macrophages produce the majority of inflammasome related cytokines (IL-18 and IL-1β) in other viral infections and play crucial roles in preventing the most severe manifestations of HSV infection in mouse models." (PMID 32101570, 2020). "Previous work in the vaccine of tuberculosis showed that the enhanced IL-1β capacity after BCG vaccination strongly correlated with a lower amount of viremia after yellow fever vaccination." (PMID 32774145, 2020). "Upon virus infection and subsequent inflammatory responses, IL-1β exhibits a broad range of biological effects, including activation of the innate immune system and modulation of the adaptive immune response." (PMID 31300043, 2019). "Direct and indirect IL-1β mediated antiviral responses have been observed in other host-virus infection models." (PMID 30736730, 2019). "VSV and HSV-1 induced expression of mRNA transcripts of cytokines, such as Il1b, Il18, Il6, and Il12, were largely comparable between WT and Park2−/− cells after viral infection." (PMID 31229895, 2019). "In our study, we first demonstrated that virus infection leads to pyroptosis by measuring activation of caspase-1 and IL-1β in human macrophages infected with MERS-CoV." (PMID 30634407, 2019). "For example, IL-1β is involved in the acute phase of inflammation, and its expression increases in tissues following bacterial or virus infections in chickens." (PMID 31288442, 2019). "Many viruses infection can induce the secretion of IL-1β to promote the development of severe inflammatory disease by activating NLRP3 inflammasome, including DENV, JEV, influenza virus, and human immunodeficiency virus type 1 (HIV)." (PMID 31474993, 2019). "The expression levels of IL-1β, IL-6, and IL-8 were significantly upregulated by virus infection, but were reduced in the compound-treated group." (PMID 31690059, 2019). "Studies delineating the molecular pathways controlling IL-1β activation and secretion by myeloid cells in response to viral infection have identified CARD9 as a key regulator of these responses." (PMID 30127791, 2018).
viral infection (continued). "During viral infection, IL-1β production is induced by cellular sensing of pathogen-associated molecular patterns (PAMPs)." (PMID 30013955, 2018). "The crosstalk signaling by IL-1β to type I IFNs in cellular homeostasis is likely of particular importance beyond virus infection to impact autoimmune development and immune regulation." (PMID 29559569, 2018). "IL-1β is an important component of the host defense against viral infection, due to its key role in innate immunity." (PMID 29317641, 2018). "Instead, the class I IFN priming phenomenon promotes a vigorous response to direct viral infection more than IL-1β or TNF-α provide." (PMID 28289923, 2017). "Noteworthy, the cytokines of crucial importance for clearing a viral infection, such as the Th1 cytokines IFNγ, and IL‐15, the pro‐inflammatory cytokines IL‐1β, IL‐6, TNFα, and TNFβ/lymphotoxin, were downregulated." (PMID 28805308, 2017). "The choice of cytokines was based on the known role of these molecules in the context of neuropathology, either by mediating inflammation (IL-6, IL-1β, TNFα, CCL5, CXCL1) and/or by their association to viral infections (IFNs)." (PMID 28330482, 2017). "Synergistic effects of IL-1β, IL-6 and TNF-α on inflammatory and stress mediators and IL-1β and IL-17 on chronic lung inflammation after viral infection have been reported." (PMID 27714503, 2017). "The benefit of melatonin in viral infections seems to be due to the immunomodulatory action in the stimulation of IL-1β, which has antiviral effects, as well as anti-oxidative and anti-inflammatory effects." (PMID 28422058, 2017). "Induction of CXCL2 and IL-1β by bites was compared to other known inducers of neutrophil influx and to virus infection alone." (PMID 27332734, 2016). "We first wanted to confirm that mosquito bite enhancement of virus infection was dependent specifically on IL-1β." (PMID 27332734, 2016). "We next investigated the ability of the proinflammatory cytokines TNF-α and IL-1β, rhinovirus infection, and polyinosinic-polycytidylic acid (polyI:C; as a mimic of other viral infections) to induce SOCS expression in BECs." (PMID 25630941, 2015). "Our observations are in line with the identification of IL-1β as a primary pro-inflammatory mediator secreted in the inflammasome in response to various triggers including bacterial as well as viral infections." (PMID 26010956, 2015). "In summary, our study has identified the gut epithelium, specifically Paneth cells, as a site of sensing and response of viral infection and an inducer of gut inflammation through IL-1β signaling during early SIV infection." (PMID 25166758, 2014). "Our study identified, for the first time, Paneth cells as an initial source of gut inflammation and IL-1β signaling during early viral infection." (PMID 25166758, 2014). "Reversal of the IL-1β induced gut epithelial damage by Lactobacillus plantarum suggests synergistic host-commensal interactions during early viral infection and identify these mechanisms as potential targets for therapeutic intervention." (PMID 25166758, 2014). "IL-1β is not only essential to innate immune defense, but is also an important mediator of adaptive immune response to viral infections." (PMID 24701032, 2014). "Using a mouse model of disease, our data shows a role for IL-1β in mediating lung dysfunction, and in driving neutrophilic inflammation during the whole phase of viral infection." (PMID 24918427, 2014). "Caspase-1 activation and IL-18 and IL-1β maturation are triggered by the assembly of these inflammasome protein complexes in response to some acute viral infections." (PMID 24788318, 2014). "Previous research demonstrated that IL-18 and IL-1β are produced upon inflammasome activation in response to some acute viral infections." (PMID 24788318, 2014).
viral infection (continued). "In order to reveal the effects of cytokines produced in response to influenza infection on virus replication, we treated moDCs with type I IFNs or proinflammatory cytokines TNF-α or IL-1β prior to H3N2 or H7N9 virus infection." (PMID 24804732, 2014). "On the other hand, there is evidence that endogenous corticosterone protects from inflammation-induced behavioral changes, given that behavioral changes due to LPS, IL-1β, and viral infection are enhanced by adrenalectomy or glucocorticoid antagonists." (PMID 25414650, 2014). "After pdmH1N1 virus infection, cigarette smoke exposed mice had significantly higher production of IL-1α, IL-1β, IL-2, IFN-γ, KC, RANTES on day 3; IL-5, IL-10 and MIP-1α both on day 1 and day 3 in the lungs than the control mice." (PMID 24465940, 2014). "After viral infection, the amount of IL1α, IL-1β and IL-18 present in the cell medium was measured by ELISA." (PMID 23723976, 2013). "The virus infection increased expression of some proinflammatory cytokines, including IL-1β and IL-8." (PMID 23637938, 2013). "Accumulating evidence has suggested that IL-1A and IL-1B play important roles in innate immunity against viral infection." (PMID 23927441, 2013). "Interleukin-1alpha (IL-1α), interleukin-1beta (IL-1β) and interleukin-18 (IL-18) have critical roles in the establishment of neutrophilic inflammation, which is commonly seen in airways viral infection and thought to be detrimental in respiratory disease." (PMID 23723976, 2013). "Transcriptional regulation of cardiac myokines in response to six weeks of de-training was previously demonstrated in Atlantic salmon, with down-regulation of TNFα, IL1β and IL6 being associated with higher survival in a viral disease challenge test." (PMID 23372811, 2013). "Beside type I interferons, pro-inflammatory cytokines such as IL-1β are also crucial effector molecules that are required to mount a proper innate immune response against viral infections." (PMID 23935506, 2013). "Meanwhile, the SNPs in TLR3, CD55, C1q and FCGR2A, TNF, LTA, IL8 and IL1B were suggested to be connected with the severity of A(H1N1)pdm09 virus infection." (PMID 23927441, 2013). "Virus infection tends to promote proinflammatory cytokine production, and elevated production of IL-1β, IL-6, and IL-8 has been detected in patients with HFMD." (PMID 23554831, 2013). "Although we show significant extracellular active IL-1β and IL-18, we also clearly demonstrate the presence of extracellular pro-IL-1β and pro-IL-18 after viral infection of cells." (PMID 23723976, 2013). "Here, we found a significantly high frequency of IL-1B rs1143627 allele C in A/H1N1 patients, suggesting the hosts with allele C were more susceptible to this virus infection." (PMID 23927441, 2013). "Similar to MARC-145 cells, the virus infection resulted in increased expression of IL-1β, IL-8, IL-10, CCL2 and CXCL10 in PAMs." (PMID 23637938, 2013). "Despite its essential role in host defense, high levels of IL-1β are also responsible for unwanted effects like fever, vasodilatation, hypotension or acute lung injury by fluid accumulation in response to viral infection." (PMID 24034559, 2013). "IL-1A and IL-1B are important inflammatory cytokines that mediate the inflammation and initiate the immune response against virus infection." (PMID 23927441, 2013). "NALP3 inflammasome assembly, caspase-1 activation and subsequent IL-1β release can be triggered by a plethora of environmental insults, including viral infections." (PMID 23935506, 2013). "Consistent with classical activation of the inflammasome by viral infection, significant levels of both IL-1β and IL-18 in their mature forms were detected in the supernatant of infected cells, and caspase-1 inhibition had an impact on this release." (PMID 23723976, 2013). "Interleukin-1β (IL-1β) is a central component of the cytokine milieu that accompanies both acute and chronic inflammation and viral disease." (PMID 23633957, 2013).
viral infection (continued). "The production of IL-6 and IL-1β after virus infection can stimulate HPA axis, which leads to the release of GCs." (PMID 22719870, 2012). "NLRP3 plays an important role in the secretion of proinflammatory cytokines interleukin 1 beta (IL-1β) and IL-18 after viral infections." (PMID 22916014, 2012). "Our data are in agreement with a role for IL-1β signaling in driving T cell effector activity during viral infection." (PMID 23209411, 2012). "To date, three distinct inflammasomes have been described to participate in IL-1β activation in response to viral infection." (PMID 23209411, 2012). "The early host response to viral infections involves transient activation of pattern recognition receptors leading to an induction of inflammatory cytokines such as interleukin-1β (IL-1β) and tumor necrosis factor α (TNFα)." (PMID 22319449, 2012). "Global microarray expression analysis displayed hallmarks of the early host response to viral infection and highlighted the prominent and rapid IL-1β/IL-6 mediated response." (PMID 22679491, 2012). "In THP-1 cells, vMyxM013-KO virus infection can co-ordinantly induce inflammasome-mediated secretion of IL-1β, and IL-18, as well as NF-κB -mediated secretion of various other pro-inflammatory cytokines and chemokines." (PMID 19851467, 2009). "Furthermore, high glucose level upregulates KDM4B, promoting NLRP3 inflammasome activation and IL-1β secretion, thus aggravating aberrant inflammation during viral infections." (PMID 41703092, 2026). "While decreasing and unchanged GBRs produced weak signatures, the increasing GBRs near IL1B-plus-budesonide-induced DEGs yielded a striking inflammatory GO signature that included terms for inflammation, viral infection, and TNFα, IL-17, NOD, and TLR signaling." (PMID 41488369, 2025). "Furthermore, by inhibiting the MAPK signaling pathway, miquelianin prevents the overproduction of cytokines, such as IL-6 and IL-1β, induced by viral infection, thereby alleviating inflammatory responses." (PMID 40165966, 2025). "Drug screening for Hippo and NLRP3/IL-1β pathways may suppress excessive inflammatory responses and intercept NETosis during viral infection." (PMID 40659620, 2025). "Chronic inflammation, triggered by bacterial or viral infections or autoimmune processes, generates an environment rich in pro-inflammatory cytokines, such as interleukin-1 beta (IL-1β), tumor necrosis factor-alpha (TNF-α), and interleukin-6 (IL-6), which directly impact cerebral endothelial cells." (PMID 40141084, 2025). "Another pro-inflammatory key player in the inflammatory response to viral infection is IL-1β." (PMID 40895576, 2025). "Moreover, platelet-secreted cytokines such as IL-1β, released upon bacterial LPS stimulation or viral infection, augment bacterial phagocytosis and further amplify macrophage-derived IL-1β production, reinforcing antimicrobial defenses." (PMID 40692784, 2025). "It was explored that this trained immunity strategy in human monocytes, and it was reported that BCG vaccination protected against experimental viral infection of yellow fever virus on the basis that the reduction in viremia was directly related to the positive regulation of IL-1β." (PMID 38576607, 2024). "This viral infection triggers an exaggerated immune response, often referred to as a cytokine storm, characterized by the excessive release of pro-inflammatory cytokines such as IL-6, IL-1β, and TNF-α." (PMID 39272485, 2024). "Viral infections frequently elevate IL-1β, which is also increased in SCZ and FEP." (PMID 39206043, 2024). "By combining imaging and spatial transcriptomics modalities, we show that respiratory sequelae post viral infections is, at least in part, a result of chronic IL-1β signaling downstream of aberrant interactions between CD8+ T cells and monocyte-derived macrophages, mediated by IFN-γ and TNF." (PMID 38077031, 2023).